CLTRN (collectrin, amino acid transport regulator)
Description:
Plays an important role in amino acid transport by acting as binding partner of amino acid transporters SLC6A18 and SLC6A19, regulating their trafficking on the cell surface and their amino acid transporter activity (By similarity). May also play a role in trafficking of amino acid transporters SLC3A1 and SLC7A9 to the renal cortical cell membrane (By similarity). Regulator of SNARE complex function. Stimulator of beta cell replication.
Synonyms: TMEM27; NX17; NX-17
Tractability: Antibody: UniProt places it where antibodies can reach, with high confidence; its Gene Ontology location is reachable by antibodies, with high confidence; UniProt predicts a signal peptide or a membrane-spanning region.
Gene: Protein-coding gene on chromosome X (15,627,085 to 15,675,377, reverse strand). Ensembl gene ENSG00000147003.
Subcellular location: Cell membrane
Subcellular location (Human Protein Atlas): Endoplasmic reticulum; Vesicles
Pathways (Reactome):
Metabolism of proteins: Insulin processing
Gene Ontology:
Molecular function: protein binding; protein homodimerization activity; transporter activator activity
Biological process: amino acid import across plasma membrane; calcium-ion regulated exocytosis; insulin secretion involved in cellular response to glucose stimulus; positive regulation of L-proline import across plasma membrane; SNARE complex assembly; positive regulation of amino acid transport
Cellular component: cytoplasm; extracellular exosome; plasma membrane; transmembrane transporter complex; brush border membrane
Homologues: Orthologues: chimpanzee CLTRN (99% identical), macaque CLTRN (95% identical), rabbit CLTRN (90% identical), guinea pig CLTRN (88% identical), rat Cltrn (86% identical), pig CLTRN (85% identical), mouse Cltrn (85% identical), dog CLTRN (84% identical), tropical clawed frog cltrn (44% identical), zebrafish cltrn (41% identical).
Diseases named in the same sentence as CLTRN in open-access papers:
CLTRN is named in the same sentence as 14 diseases in open-access papers, as found by Europe PMC text mining. Sharing a sentence is not in itself a finding about the gene and the disease. The quoted sentences say what the papers report.
hepatocellular carcinoma (1 paper, 2022). A malignant tumor that arises from hepatocytes. "Transmembrane protein 27 (CLTRN, also known as TMEM27) is a type Ia transmembrane, which can be regulated by the Nrf-1/RAN/DLD protein complex to deplete GSH and enhance the radiosensitivity of hepatocellular carcinoma (HCC) cells." (PMID 36176274, 2022).
CLTRN also shares sentences with these, for which no sentence is quoted: cancer (3 papers); tumor (3); COVID-19 (2); diabetes (2); type 2 diabetes (2); acute kidney injury (1); head and neck squamous cell carcinoma (1); infection (1); liver cancer (1); metabolic syndrome (1); mycoplasma infection (1); Obesity (1); renal cell carcinoma (1).